FN1 (fibronectin 1)
Diseases named in the same sentence as FN1 in open-access papers (continued):
Sharing a sentence is not in itself a finding about the gene and the disease.
gastric cancer (continued). "To investigate whether FN1 was involved in the FENDRR–induced decrease in gastric cancer cell metastasis, we carried out rescue experiments." (PMID 25167886, 2014). "FN-1 promotes invasion of gastric cancer cells through interaction with α5β1 integrin." (PMID 25350954, 2014). "We also confirmed that FN1 knockdown inhibits cell mobility in the gastric carcinoma cell line." (PMID 25167886, 2014). "In gastric cancer (GC), circ_0000285 suppresses miR‐1278 via sponging effects, and miR‐1278 suppresses FN1 expression via binding to its 3’UTR." (PMID 35535385, 2022). "In gastric cancer, miR-200c specifically binds to the 3′-UTR of FN1 and KLF6, thereby downregulating their expression and affecting the proliferation, migration, and invasion of gastric cancer cells." (PMID 39859424, 2025). "Through scSDNE analysis, we also elucidated L-R interactions between fibroblasts and immune cells—particularly macrophages—in gastric cancer, where interactions of CD44 with collagen family genes and FN1 emerged as key mechanisms for information exchange." (PMID 40333631, 2025). "Previous studies have found that FN1 as well as ITGA5 could facilitate tumor angiogenesis and progression in cervical cancer and may be a prognostic risk factor in many types of cancer including Gliomas, gastric cancer, head and neck squamous cell carcinoma and NSCLC." (PMID 38730286, 2024). "In a previous study, we identified six key CAF markers: collagen types COL3A1, COL1A2, COL1A1, COL5A1, and FN1, and SPARC as the pivotal poor prognostic markers in gastric cancer." (PMID 38562556, 2024). "Microarray-based bioinformatics studies revealed increased expression of CAF markers Fibronectin 1 (FN1), Serine proteinase inhibitor 1 (SERPINE1), and secreted protein acidic and cystine-rich (SPARC) genes in gastric cancer patients with low survival." (PMID 38562556, 2024). "We identified ECM components COL1A1, COL1A2, COL3A1, COL5A1, FN1, and SPARC as the pivotal CAF markers in gastric cancer, which were separately reported as biomarkers of gastric cancer in different studies." (PMID 35739492, 2022). "Several paired genes including (f2r, islr), (fn1, col1a1), (islr, col1a1), (islr, f2r), (pdgfrb, col1a1), (pdgfrb, f2r), and (vcan, col1a1) showed a positive correlation with each other, so that using antagonists against both of them could have a synergistic effect on the gastric cancer survival." (PMID 35650297, 2022). "Eight out of 38 upregulated genes in gastric cancer (ASPN, COL1A1, COL1A2, COL3A1, COL5A1, FAP, FN1, and SPARC) overlapped with the CAF markers list (circos plot on the left)." (PMID 35739492, 2022). "In this study, we identified the six key CAF markers namely COL1A1, COL1A2, COL3A1, COL5A1, FN1, and SPARC in gastric cancer that can be used as predictors of CAF infiltration and prognostic biomarkers in gastric cancer." (PMID 35739492, 2022). "In gastric cancer, FENDRR was found to increase cell migration and invasion via up-regulation of FN1, MMP2 and MMP9." (PMID 35183135, 2022). "Deregulation of protein expression, such as FN1 and ADAM9 (upregulated) or SPARCL-1 (downregulated), has been shown to affect cell growth and tissue proliferation in gastric cancer." (PMID 36672527, 2022). "Our study revealed the COL1A1, COL1A2, COL3A1, COL5A1, FN1, and SPARC as the key CAF markers in gastric cancer." (PMID 35739492, 2022). "miR647 modulates FBLN1, FN1, and MST1R genes and has a tumor-promoting role in gastric cancer via repression of TP73." (PMID 34357026, 2021). "In summary, FBN1, FN1, HGF, MMP9, THBS1, and VCAN can be used as new target genes to observe the prognosis of gastric cancer." (PMID 33014013, 2020). "Our results showed that the abnormal expression of FN1, TIMP1, SPP1, APOE, and VCAN influenced the prognosis of patients with gastric cancer." (PMID 33015179, 2020).
gastric cancer (continued). "Many mechanisms were reported to be involved in CDDP resistance of human gastric cancer, such as miR-101/VEGF-C pathway, miR-34a/PI3K/AKT/survivin pathway, miR-1271/IGF1R, IRS1, mTOR, BCL2 pathway, and circ-FN1/miR-182-5p pathway." (PMID 32855967, 2020). "The results showed that FN1, TIMP1, SPP1, APOE, and VCAN were related to OS in gastric cancer patients (p < 0.01)." (PMID 33015179, 2020). "We herein identified a large number of genes associated with the ECM and cell adhesion to be differentially expressed in intestinal gastric cancer, including TIMP1, MMP7, FN1, SPARC, LUM and BGN, which were upregulated." (PMID 29484116, 2018). "Four hub genes with worse overall survival (OS) of gastric cancer patients were detected and the Kaplan Meier-plotter was applied to visualize them, including BGN, MMP2, COL1A1 and FN1." (PMID 29050278, 2017). "Histone deacetylation was involved in the down-regulation of FENDRR in gastric cancer cells and FENDRR overexpression suppressed invasion and migration by down-regulating FN1 and MMP2/MMP9 expression." (PMID 29069754, 2017). "FN1 and LAMC1 ligands include integrin, a regulator of cell adhesion and a prognostic factor of gastric cancer." (PMID 27487135, 2016). "Expression of adhesion-related molecules, such as fibronectin 1 (FN1) and laminin gamma 1 (LAMC1), were increased in mesothelial cells after internalization of TEX from gastric cancer cell line and malignant pleural effusion." (PMID 27487135, 2016). "FENDRR is down-regulated in gastric cancer, and decreased expression of FENDRR induces FN1 expression, which resulted in activation of MMP2/MMP9." (PMID 26238992, 2015). "To assess the relationship between FN1 and FENDRR expression in gastric cancer, we examined FN1 expression by qPCR and immunohistochemistry in 40 paired gastric cancer tissues and in 5 gastric cancer cell lines." (PMID 25167886, 2014). "Subsequently, the increased FN1 expression contributes to the activation of MMP2/MMP9, leading to higher migration and invasion potential of gastric cancer cells, which was manifested by the greater number of metastatic nodules in the nude mice." (PMID 25167886, 2014). "A recent study reported that FN1 mRNA 3′‐UTR could facilitate the invasion and metastasis of gastric cancer." (PMID 40638546, 2025). "Furthermore, NRP-1 was shown to directly interact with fibronectin-1 (FN1), which promotes epithelial-mesenchymal transition (EMT) in gastric cancer cells." (PMID 40430075, 2025). "It is the first study that clarify that FN1 could suppress the binding of RAP1B to PARK2 to stabilise RAP1B protein, thereby activating Akt signalling pathway and promoting gastric cancer migration and metastasis." (PMID 40638546, 2025). "Among the proteins that showed a negative correlation with overall survival, fibronectin 1 (FN1) indicates poor prognosis in gastric cancer." (PMID 39075362, 2024). "Besides, high expression of five genes, POSTN, COL5A2, COL1A1, FN1, and MMP2, was revealed by Kaplan–Meier survival curve analysis to suggest a poor prognosis for gastric cancer patients." (PMID 37461041, 2023). "Moreover, the MSLN, SPP1, THBS2, SPARC, FN1, IGFBP7, VCAN were up-regulated in gastric carcinoma samples, while FGA was down-regulated." (PMID 36842141, 2023). "Hence the module analysis strengthened the connection of the six CAF markers: COL1A1, COL1A2, COL3A1, COL5A1, FN1 and, SPARC, with the 3 KEGG pathways: ECM-receptor interaction, focal adhesion and, PI3K-Akt signaling pathway in gastric cancer." (PMID 35739492, 2022). "The results showed that 8 up-regulated genes (FN1, COL3A1, FBN1, BGN, COL5A2, THBS2, COL5A1 and SPARC) and 1 down-regulated gene (ATP4A) may be the central genes in gastric cancer." (PMID 32742441, 2020).
gastric cancer (continued). "Furthermore, five of them (FN1, TIMP1, SPP1, APOE, and VCAN) were found to be related to gastric cancer." (PMID 33015179, 2020). "Using a robust proteomic approach, we identified numerous molecules secreted into the omental tissue conditioned medium (CM) which may promote gastric cancer cellular aggressiveness (i.e., IL-6, IL-8, MMP9, FN1, and CXCL-5)." (PMID 31803630, 2019). "LINC00152 could directly bind to EGFR and activate EGFR signaling pathway and FENDER could suppress cell invasion and migration by downregulating FN1 and MMP2/MMP9 expression in gastric cancer." (PMID 27966444, 2016). "Further insights into the functional and clinical implications of FENDRR and its targets FN1 and MMP2/MMP9 may help with the treatment of gastric cancer." (PMID 25167886, 2014). "Data also showed that high expressions of fibronectin 1 (FN1), the tissue inhibitor of metalloproteinases 1 (TIMP1), secreted phosphoprotein 1 (SPP1), apolipoprotein E (APOE), and versican (VCAN) were related to a poor overall survival in gastric cancer patients." (PMID 33015179, 2020).
pulmonary fibrosis (75 papers, 2008 to 2025). Chronic progressive interstitial lung disorder characterized by the replacement of the lung tissue by connective tissue, leading to progressive dyspnea, respiratory failure, or right heart failure. "Genes involved in pulmonary fibrosis processes found to be upregulated in CIPF compared with healthy WHWTs in cluster M1 included FN1, SPP1, CXCL8, and PLAU (encoding plasminogen activator urokinase)." (PMID 33384697, 2020). "Our previous studies showed that increased FN deposition is linked with lung fibrosis, and we show in the current study that increased FN1 mRNA transcripts are present in lung tissues from lung fibrosis patients." (PMID 32664949, 2020). "Polymorphisms and mutations in the FN1 gene have shown to possess an association with renal glomerulopathy, spondylometaphyseal dysplasia, lung fibrosis in systemic sclerosis, and knee osteoarthritis." (PMID 32285152, 2020). "We identified four overexpressed genes associated with pulmonary fibrosis processes in CIPF compared with healthy dogs in this cluster including FN1, SPP1, CXCL8, and PLAU." (PMID 33384697, 2020). "In particular, Mmp 7 and Fibronectin 1 have recently been assigned a causative role in pulmonary fibrosis and shown to be expressed in interstitial fibroblasts and ATII cells." (PMID 18478089, 2008). "In addition to the upregulation of typical fibrosis-associated genes (Col1a1, Fn1 and Acta2), an increase in Prrx1a and Prrx1b mRNA expression was previously reported during fibrosis development in the bleomycin model of lung fibrosis." (PMID 40856011, 2025). "Additionally, upregulation of FN1 has been associated with fibrosis in inflammatory orbital diseases 45, hepatic fibrosis 46, idiopathic pulmonary fibrosis 47,48 and liver fibrosis." (PMID 27438566, 2016). "The fibronectin-1 pathway represents another matrix remodeling finding previously observed in smoking with implications in pulmonary fibrosis, epithelial mesenchymal transition (EMT) and COPD." (PMID 40236402, 2025). "At 21 d.p.i., deletion of both Yap and Taz in myofibroblasts strongly attenuated lung fibrosis and suppressed the expression of key myofibroblast activation and profibrotic genes, including Acta2, Col1a1, Postn, Fn1, Col3a1, and Tgfb1." (PMID 40454481, 2025). "Undoubtedly, both gene and protein levels of TGF-β1 and Fn1 appeared significantly elevated (p < 0.05), further confirming the occurrence of early pulmonary fibrosis-like changes in mice after heat exposure." (PMID 38474239, 2024). "The gene of FN1, known to be a driver of pulmonary fibrosis, was reported to be up‐regulated in COVID‐19 survivors." (PMID 37807299, 2024). "Both transforming growth factor beta 1 (TGFβ1) and fibronectin 1 (FN1) are known to be drivers of pulmonary fibrosis." (PMID 35288537, 2022). "Unsurprisingly, qRT-PCR of Col1a1, and Fn1 also indicated that the TL treated mice exhibited a lower degree of lung fibrosis than the BIM treated mice." (PMID 33995084, 2021). "We further found that lung fibrosis and the expression of fibrosis genes, including Col1a1, Col3a1 and Fn1, an outcome mediated by the accumulation of senescence, were reduced by SSK1 treatment." (PMID 32341413, 2020). "Inhibiting a main functional domain of the FN1 gene inhibits fibrosis features in an in vivo model of lung fibrosis." (PMID 32664949, 2020). "In another study, an upregulation of fibronectin-1, a gene related to lung fibrosis, was observed in mice in an inhalation chamber with PHMG-P over 10 weeks." (PMID 32370250, 2020). "NOX-4 is an important profibrotic signal implicated in aberrant fibroblast activation in idiopathic pulmonary fibrosis, and TGF-β1-mediated collagen type I gene, α-SMA, and fibronectin-1 gene expressions were Nox4-dependent." (PMID 30915142, 2019). "SC-43 treatment decreased FN1 expression in M2 macrophages suggesting another possibility, i.e., that SC-43 may contribute to mitigation of pulmonary fibrosis by inhibiting fibroblast recruitment." (PMID 37291088, 2023).
pulmonary fibrosis (continued). "SARS-CoV-2 infection increased ACE2, TGFB1, CTGF and FN1 mRNA that were drivers of lung fibrosis." (PMID 32664949, 2020). "FN1 inhibitors, including monoclonal antibodies and small molecules, modulate cell behavior, reduce inflammation, and may reverse fibrosis, with therapeutic applications in fibrotic diseases such as liver cirrhosis, pulmonary fibrosis, and kidney fibrosis." (PMID 40809316, 2025). "Fibrosis-related genes include Col1a1, Acta2, Fn1, and Tgfb1 gene, and senescence-related genes composed of Cdkn2a, Tnf, Serpine1, Ccl2, Mmp10, and Mmp12 gene, all of which reflected the intensity of lung fibrosis and senescence events in lung tissue and pulmonary fibroblasts." (PMID 35662697, 2022). "Fibronectin 1 (Fn1), a key ECM component in pulmonary fibrosis, was upregulated upon TGF-β1 stimulation, along with Acta2, Col1a1, and Col3." (PMID 40867551, 2025). "Specifically, we propose that enhanced TGF-β signaling of LOY-macrophages stimulates FN1-mediated activation of fibroblasts and their differentiation to myofibroblasts, resulting in enhanced ECM production and lung fibrosis." (PMID 40581694, 2025). "The results demonstrated a significant rise in the mRNA levels of Fn1 and α-SMA in the TGF-β1-stimulated group compared to the control group, indicating the successful establishment of an in vitro model of lung fibrosis." (PMID 40630478, 2025). "Western blot analysis of the lung tissues found that the levels of pulmonary fibrosis markers including α-SMA, p-Smad3 and Fn1 were higher in RTN3-null group than in Wild type group after bleomycin treatment." (PMID 39972424, 2025). "Meanwhile, we also examined the gene and protein expression of lung fibrosis-related molecules (TGF-β1, Fn1, and Col1a1)." (PMID 38474239, 2024). "Using primary human lung cells, we show that SARS‐CoV‐2, and to a lesser degree SARS‐CoV, perturbs abundance of pulmonary fibrosis‐related proteins such as SERPINE1/PAI1, FN1, and HSPG2." (PMID 35833542, 2022). "To further determine the effect of A2BAR in the lung fibrosis of MWCNT exposure, we examined the protein level of two major ECM proteins (collagen I and fibronectin 1 (FN1))." (PMID 30922349, 2019). "FN-1 and LGALS3 are known to participate in pulmonary fibrosis and be produced by fibroblasts and endothelial cells, and now by human HPM cells." (PMID 27459687, 2016). "Consequently, TGF-β is commonly employed to culture human lung fibroblasts (HLFs) to create the in vitro models of lung fibrosis, and α-SMA and Fn1 are frequently used to assess the extent and progression of fibrosis." (PMID 40630478, 2025). "Lung fibrosis was observed in the lungs of heat-exposed mice, with extensive collagen deposition and the elevated expression of fibrosis molecules, including transforming growth factor-β1 (TGF-β1) and Fibronectin (Fn1) (p < 0.05)." (PMID 38474239, 2024). "Additionally, FN1 interacts with the Angiotensin-converting enzyme 2 (ACE2), which is related to SARS-CoV-2 binding, and is up-regulated in lung tissue from lung fibrosis patients." (PMID 37233676, 2023). "Next, to evaluate whether SAHA could also inhibit TGF-β1-driven differentiation, we analyzed by qRT-PCR many markers of lung fibrosis, such as TGF-β1, aSMA and FN1." (PMID 30042393, 2018). "Ifnar1-/- mice did not display enhanced lung cell influx and lung fibrosis as shown by representative lung histology and Ascroft fibrosis score and the expression of the extracellular matrix protein fibronectin (Fn1)." (PMID 33488589, 2020). "Interestingly, FN1+SPP1+ monocyte-derived macrophages are believed to be involved in the pathogenesis of canine idiopathic pulmonary fibrosis and profibrotic SPP1+ monocyte-derived macrophages were also reported in human COVID-19, pulmonary fibrosis and lung cancer." (PMID 40114924, 2025).
pulmonary fibrosis (continued). "Nonetheless, the expression of CSF1R, MRC1, and FN1 exhibited a significant reduction following SC-43 treatment, implying that SC-43 may inhibit the CSF1R/STAT3 signaling pathway and diminish the expression of fibrotic genes within macrophages in vivo during the pulmonary fibrosis progression." (PMID 37291088, 2023).